EPS8 (EGFR pathway substrate 8, signaling adaptor)
Diseases named in the same sentence as EPS8 in open-access papers (continued):
Sharing a sentence is not in itself a finding about the gene and the disease.
autism (1 paper, 2018). Persistent deficits in social interaction and communication and interaction as well as a markedly restricted repertoire of activity and interest as well as repetitive patterns of behavior. "Lastly, Eps8 protein, which is downstream of BDNF and activates the Rac pathway important for synaptic plasticity, is decreased in idiopathic autism, and knockout of Eps8 in a mouse model resulted in spine abnormalities, decreased LTP and autism-like behavior." (PMID 29691724, 2018). "Because BDNF/TrkB-mediated signaling pathways, including Akt-mTOR and Eps8-Rac, play a key role in the development of the cortex and in synaptic function and plasticity, altered BDNF/TrkB signaling through these pathways may be an important contributor to autism pathogenesis." (PMID 29691724, 2018).
Cognitive impairment (1 paper, 2014). Abnormal cognition is characterized by deficits in thinking, reasoning, or remembering. "Mice lacking Eps8 display abnormal growth of immature spines and cognitive impairment." (PMID 24533597, 2014).
cutaneous squamous cell carcinoma (1 paper, 2014). "As Eps8 is reported to be increased in oral SCC, we next investigated whether Eps8 expression levels were increased in human cutaneous squamous cell carcinoma cells." (PMID 25359883, 2014).
depression (1 paper, 2022). "The inconsistency may be due to expression trend in depression and cancer subjects, and also due to expression differences of Eps8 and three analogs." (PMID 35771226, 2022).
esophageal cancer (1 paper, 2010). A primary or metastatic malignant neoplasm involving the esophagus. "The expression level of downstream targets of p66shc i.e., eps8 and rac1 was also found to be consistently higher in human esophageal carcinomas, and hence correlated positively with p66shc expression." (PMID 20565814, 2010). "In the present report, we focus on the expression pattern of p66shc and its downstream targets i.e., Eps8 and rac1 proteins in human esophageal carcinomas (one of the most common cancer worldwide)." (PMID 20565814, 2010).
glioma (1 paper, 2020). A benign or malignant brain and spinal cord tumor that arises from glial cells (astrocytes, oligodendrocytes, ependymal cells). "Bioinformatics analysis showed that high levels of MLK3 and EPS8 in gliomas are correlated with a significantly worse overall survival in patients." (PMID 33692940, 2020). "Furthermore, we provided a novel mechanism by which MLK3 facilitates glioma cell migration by regulating actin skeleton remodeling via MLK3/EPS8 signaling." (PMID 33692940, 2020). "In addition, this study demonstrated that MLK3 cooperates with EPS8, which might aid in prognosis prediction for patients with gliomas." (PMID 33692940, 2020). "In addition, MLK3 cooperates with EPS8 and affects the overall survival of patients with gliomas." (PMID 33692940, 2020).
Huntington disease (1 paper, 2025). Huntington disease (HD) is a rare neurodegenerative disorder of the central nervous system characterized by unwanted choreatic movements, behavioral and psychiatric disturbances and dementia. "In this study, we found that age-associated hyperactivation of EPS8/RAC signaling in Caenorhabditis elegans promotes the pathological aggregation of Huntington’s disease-related polyglutamine repeats and ALS-associated mutant FUS and TDP-43 variants." (PMID 40903652, 2025).
hypoparathyroidism (1 paper, 2024). Hypoparathyroidism is an endocrine disorder in which the parathyroid glands in the neck do not produce enough parathyroid hormone (PTH). "In LER (CD−M2), Ush1c, Otogl, Gjb2, and Eps8 were associated with NSHL; Ush1c and Clrn1 with Usher syndrome, Six1 with branchiootorenal syndrome; Gjb2 with skin phenotype and HL; Gata3 with hypoparathyroidism, sensorineural hearing loss, and renal dysplasia; and Col9a2 with Stickler syndrome." (PMID 39684410, 2024).
lung squamous cell carcinoma (1 paper, 2025). "Recent findings have shown ALDH7A1 expression in PDAC can additionally be regulated post-transcription through interaction with epidermal growth factor receptor kinase substrate 8 (EPS8), inhibiting proteasomal degradation, and via DNA-methylation in lung squamous cell carcinoma." (PMID 40524738, 2025).
melanoma (1 paper, 2015). A malignant, usually aggressive tumor composed of atypical, neoplastic melanocytes. "The ‘blebbing’ caused by Eps8 is turned on by another protein called Erk that is often overactive in melanoma cells." (PMID 26163656, 2015). "To determine the role of Eps8 in cancer cell blebbing and migration, we utilized human A375 melanoma cells which carry a mutation in B-Raf (V600E) that activates the Raf/MEK/Erk pathway." (PMID 26163656, 2015). "The work described here elucidates the importance of a specific Erk effector, Eps8, in the migration of confined melanoma cells." (PMID 26163656, 2015). "We demonstrate that, in contrast to cells adhered to ECM where Eps8 associates with filopodia and lamellipodia, in non-adherent melanoma cells, Eps8 localizes to bleb membranes as actin assembles." (PMID 26163656, 2015). "Our demonstrations that Erk activity and regional regulation of Eps8 activity are essential to leader bleb formation suggests that Erk activity itself may be regionally regulated in migrating melanoma cells." (PMID 26163656, 2015). "Thus, our results identify a mechanism by which spatial regulation of Eps8 actin regulatory activities by Erk may promote the rapid, unregulated migration of melanoma cells that may be critical to their highly invasive behavior in vivo." (PMID 26163656, 2015). "We find that the bundling activity of Eps8 is required for promoting the mesenchymal-to-leader bleb transition in confined, non-adherent melanoma cells." (PMID 26163656, 2015). "Thus, Eps8 shows differential localization to actin structures in adherent spread and non-adherent blebbing melanoma cells." (PMID 26163656, 2015). "Erk-dependent phosphorylation of Eps8 on S624 and T628 has been shown to inhibit actin capping by Eps8 without altering its filament binding activity, and our above results suggest that capping may be regionally regulated in melanoma cells migrating under non-adhesive confinement." (PMID 26163656, 2015).
tongue cancer (1 paper, 2019). A malignant neoplasm affecting the tongue. "Alterations in ANO1, NUDCD1, PIK3CA defined survival in tongue cancer patients with nodal metastasis (node+ECS-), while EPS8 is a significant differential in node+ECS- laryngopharyngeal cancers." (PMID 31310629, 2019).
triple-negative breast carcinoma (1 paper, 2023). An invasive breast carcinoma which is negative for expression of estrogen receptor (ER), progesterone receptor (PR), and human epidermal growth factor receptor 2 (HER2). "PTK6 has also been shown to promote cell proliferation and migration through phosphorylation of Eps8, regulate the expression of E-cadherin through SNAIL protein degradation, promote epithelial mesenchymal transformation and regulate the metastasis of triple-negative breast cancer cells." (PMID 37932734, 2023).
cancer (36 papers, 2010 to 2026). A tumor composed of atypical neoplastic, often pleomorphic cells that invade other tissues. "Eps8 depletion had similar effects on cancer-associated phenotypes to those seen upon deletion of FAK in SCC cells, including impaired polarization and invasive migration, with there were no visible effects on random cell migration." (PMID 25359883, 2014). "We next investigated the role of Eps8 in FAK-mediated cancer-associated phenotypes, such as migration, polarization and invasion through Matrigel." (PMID 25359883, 2014). "Because EPS8 influences many genes involved in the development and progression of human cancers, we decided to examine whether EPS8 regulates targets associated with these processes in AML cell lines." (PMID 29357910, 2018). "Furthermore, elevated expression of Eps8 has been variously linked to tumorigenesis, proliferation and migration, and represents a poor prognosis in patients with cancer." (PMID 28881704, 2017). "Furthermore, proteins involved in filopodia formation such as Fascin, Eps8 and Irsp53 have been shown to be associated with increased invasiveness of cancer cells." (PMID 25875301, 2015). "Furthermore, EPS8 downregulation, through mithramycin treatment, causes a significant decrease in cancer cell growth and migration ability." (PMID 24367505, 2013). "While we used NEO1 as an example, several other genes known to have roles in cancer proliferation and various pathway cascades were identified within these shared compartments, including EPS8, FAM92A, IRS1, and SETBP1." (PMID 37016431, 2023). "Epidermal growth factor receptor pathway substrate 8 (EPS8) modulates cancer cell proliferation and apoptosis." (PMID 37067729, 2023). "Both the Forkhead box (FOX) M1 transcription factor and the Epidermal Growth Factor (EGF) receptor Pathway Substrate 8 (EPS8) are known to be activated by mitogenic signaling and their levels upregulated in cancer." (PMID 30941306, 2019). "In the present study, we focused on the EGFR/Eps8 complex as a promising tumor target for cancer therapy." (PMID 31118055, 2019). "Initially, to screen the expression levels of EGFR and EPS8 in cancer and normal cell lines, we performed a western blot analysis." (PMID 31118055, 2019). "EPS8 is constitutively tyrosine-phosphorylated in human cancer cell lines and over-expression of EPS8 was able to transform NIH3T3 cells in focus forming assay." (PMID 30941306, 2019). "Cancer cells express high levels of Eps8 and EGFR among the cell lines that we have examined were treated with peptide 327 and TAT-327 (50 μM) for 12 h." (PMID 29515106, 2018). "Eps8 is an actin regulatory scaffold protein whose expression is increased in SCC and is associated with the aggressive cancer phenotype." (PMID 29966311, 2018). "In the present study, we focused on Eps8 as a promising tumor antigen that drives induction of CTL responses against cancer cells." (PMID 29515106, 2018). "By combining imaging of fluorescently tagged proteins and atomic force microscopy (AFM) with targeted mutations in Eps8, the work described here tests the hypothesis that Eps8 acts as a key effector of Erk to modulate actin cortex mechanics and thereby mediate bleb-based migration of cancer cells." (PMID 26163656, 2015). "We show here that in cancer cells, the actin capping and bundling scaffold protein Eps8 is required to promote this morphological transition under confinement by enhancing cortical tension and promoting increased intracellular pressure." (PMID 26163656, 2015). "Our observation that inhibition of Erk activity is capable of blocking formation of large leader blebs is consistent with the notion that effectors of the pathway, such as Eps8, are important to the migration of confined cancer cells." (PMID 26163656, 2015). "Eps8 expression is increased in several different cancer types, such as pancreatic cancer and oral squamous cell carcinoma." (PMID 25359883, 2014).
cancer (continued). "This is supported by the fact that impairment of FAK binding to Eps8 inhibits invasion, implying that the FAK–Eps8 complex is important in cancer cell phenotypes." (PMID 25359883, 2014). "Eps8 has previously been found in lysosomes and is subject to chaperone-mediated autophagy in cancer cells, suggesting that its cellular levels also need to be tightly regulated by lysosomal degradation pathways." (PMID 25359883, 2014). "Next, we addressed the role of Eps8 in cell polarization towards a wound in a confluent monolayer, and in permitting cancer cell invasion into, and through, Matrigel in response to serum used as a chemoattractant." (PMID 25359883, 2014). "Overall, our data indicate a key role for Eps8 as a component of Src and FAK biochemical complexes that control the FAK-dependent actin-associated cancer phenotypes of polarization and invasive migration." (PMID 25359883, 2014). "Eps8 and FAK participate in a complex at focal adhesions that promotes actin-associated cancer phenotypes, including direction sensing and invasive migration." (PMID 25359883, 2014). "We observed a higher level of Eps8 expression in well, moderately and poorly differentiated cancers." (PMID 20565814, 2010). "Silencing of Gal3and c-Abl/Arg rendered MCF7 cells more susceptible to apoptosis, resulting inreduced tumor growth.Likewise, the epidermal growth factor receptor pathway substrate 8 (Eps8),implicated in tumor promotion and metastasis, was proposed as a CMA substrate inhuman cancer cells." (PMID 38829285, 2024). "Much focus has been put on understanding how EPS8 exerts regulatory effects on cell ruffling and how EPS8 upregulation in cancer cells stimulates cell migration and metastasis, but its nuclear role remains unclear." (PMID 30941306, 2019). "We further hypothesized that the EGFR/Eps8 complex inhibitor could negatively affect the survival of cancer cells by suppressing the downstream signaling of EGFR/Eps8." (PMID 31118055, 2019). "Furthermore, the aberrant expression of Eps8 often suggests anunfavorable prognosis for cancer patients." (PMID 31118055, 2019). "Our data suggest that the EGFR/Eps8 complex offers a novel cancer drug target." (PMID 31118055, 2019). "The EGFR/Eps8 complex is involved in regulating cancer progression and might be an ideal target for antitumor therapy." (PMID 31118055, 2019). "The epidermal growth factor receptor (EGFR) pathway substrate 8 gene (Eps8) is involved in regulating cancer progression and might be an ideal antigen." (PMID 29515106, 2018). "EPS8 is important in regulating the development and progression of many human cancers." (PMID 29357910, 2018). "In our study, we investigated whether blocking the interaction of Eps8 with EGFR could have a biological effect in cancer cells." (PMID 29515106, 2018). "Since Eps8 exposes the imperative function in cancer progression, future research may accelerate protein degradation of Eps8 by CMA in cancer cells." (PMID 28881704, 2017). "ITSN deficiency leading to impaired Cbl-Eps8 interaction, and enhanced mSos1-Eps8 complex formation leading to Rac1 activation, is a mechanism which has not been previously reported in cancer." (PMID 27629044, 2016). "Our results identify a mechanism by which Eps8 may promote the transition to rapid, unregulated migration of cancer cells in confinement that may be critical to their highly invasive behavior in vivo." (PMID 26163656, 2015). "Our study shows for the first time a critical role for Eps8 and its regulation of the actin cytoskeleton in promoting cell cortex tension and intracellular pressure to induce the rapid, adhesion-independent migration of confined cancer cells." (PMID 26163656, 2015). "We tested the hypothesis that Eps8 acts as an Erk effector to modulate actin cortex mechanics and thereby mediate bleb-based migration of cancer cells." (PMID 26163656, 2015).
cancer (continued). "We then sought to determine whether the requirement for Eps8 in leader bleb-based migration was a more general property of cancer cells or specific to A375 cells." (PMID 26163656, 2015). "The 97-kDa isoform of Eps8 has been variously linked to proliferation, migration and oncogenic transformation, implying that the roles of Eps8 role in cancer cell phenotypes is complex and might be dependent on context." (PMID 25359883, 2014). "Hence, we do not rule out the possibility of p66shc participating in the development of cancers through Grb2-Ras pathway in addition to operating through Eps8-Rac1 pathway." (PMID 20565814, 2010). "It is possible that this relationship between Rac1-mediated increase in p66shc might lead to an increase in expression of Eps8, which eventually might lead to the development of cancer." (PMID 20565814, 2010). "Therefore, Eps8 is considered a novel potential target for specific cancer therapy." (PMID 31118055, 2019). "Therefore, Eps8 has been considered an attractive target for specific cancer immunotherapy." (PMID 29515106, 2018). "Epidermal growth factor receptor pathway substrate 8 (Eps8) is an actin bundling and capping protein that plays a critical role in development of the nervous, auditory and reproductive systems and its upregulation in cancers correlates with invasivity and poor prognosis." (PMID 26163656, 2015). "In Pt2, five integrations with total frequencies of more than 1% were observed near or in cancer-related genes (DPP4, TNFAIP3/PERP, MLLT10, EPS8, and SPINT1)." (PMID 34786435, 2021). "ABI1 can regulate actin aggregation and cytoskeleton reconstruction by forming complexes with WAVE2, PI3K, EPS8, and/or N-WASP17,20,23,24, and thus play an important role in the metastasis of various malignant tumors including CRC8–12,27,29,37." (PMID 34031495, 2021). "Epidermal growth factor receptor kinase substrate 8 (Eps8), which is an adaptor protein of tyrosine kinase receptors, including EGFR, is reported to be involved in the pathogenesis of cancer." (PMID 32456226, 2020). "Our data link stress chaperone induction with PI3K/AKT signaling activation and Eps8-mediated actin remodeling that orchestrate TNT formation and intercellular communication for the survival of cancer cells under stress." (PMID 31127190, 2019). "In FAK-proficient SCC cells, active Src becomes tethered at FAs, where both Eps8 and Ambra 1 are recruited and required for FAK-dependent cancer processes like adhesion, invasion, polarization, and 3D proliferation." (PMID 29966311, 2018). "Therefore, EPS8 might represent a novel potential target for cancer therapy." (PMID 29357910, 2018). "Here, we have addressed the role of Eps8 in control of FAK- (also known as PTK2) and Src-dependent phenotypes in a well-defined cancer cell system." (PMID 25359883, 2014). "We found unequivocally that Eps8 gene product(s) are elevated in mouse SCC cell lines when compared to normal keratinocytes, and in patient-derived carcinomas, transplantation-induced SCCs and metastases." (PMID 25359883, 2014). "For instance, EPS8 has also been shown to upregulate FOXM1, an important factor in the development and progression of certain cancers which is known to directly bind with Sp1." (PMID 24367505, 2013). "Eps8 is a substrate of EGFR and has been shown to be involved in regulating cancer progression." (PMID 37169593, 2023). "We argued that EPS8 is a novel partnering factor required for FOXM1 to exert its multiple roles in cancer cell proliferation and migration/invasion, and targeting the FOXM1-EPS8 interaction might provide an alternative anti-cancer strategy." (PMID 30941306, 2019). "Notably, only two genes (EPS8 and FAXDC2) were downregulated in cancer tissues compared with normal controls." (PMID 31794425, 2019). "By inhibiting the Eps8/EGFR interaction, peptide 327 and TAT-327 may serve as novel peptide inhibitors, which could provide an innovative approach for treating various cancers." (PMID 29515106, 2018).